CCND2 (cyclin D2)
Diseases named in the same sentence as CCND2 in open-access papers (continued):
Sharing a sentence is not in itself a finding about the gene and the disease.
cervical carcinoma (continued). "To investigate the expression pattern of CCND2 AS1 in cervical cancer tissues, we performed qRT-PCR analysis of 46 pairs of cervical cancer tissues and nearby non-tumor tissues." (PMID 32607313, 2020). "We confirmed this to be the case by examining cervical cancer cell lines in vitro, which revealed that CCND2 AS1 overexpression or knockdown led to inhibition or promotion, respectively, of cell proliferation." (PMID 32607313, 2020). "Remarkably, our results have identified CCND2 as a direct miR-206 target in cervical cancer cells." (PMID 34746018, 2021). "Therefore, CCND2 is overexpressed in cervical cancer tissues and increases cervical cancer cell viability after CDDP exposure." (PMID 34746018, 2021). "In cervical cancer tissues, the expression of miR-206 and CCND2 was inversely correlated." (PMID 34746018, 2021). "The cisplatin-resistant cervical cancer cells expressed higher CCND2 expression than the parental cells, whereas inhibition of CCND2 could sensitize the resistant cells to cisplatin treatment." (PMID 34746018, 2021). "However, its functional roles in mediating CDDP resistance, and the mechanisms that control the expression of CCND2 in cervical cancer cells, remain poorly undefined." (PMID 34746018, 2021). "Recently, CCND2 was shown to facilitate the malignant properties of cervical cancer cells." (PMID 34746018, 2021). "Although CCND2 could increase the proliferation and migration of cervical cancer cells, it remains unclear whether CCND2 mediates CDDP resistance in cervical cancer cells." (PMID 34746018, 2021). "We speculated that miR-206 may increase the sensitivity of cervical cancer cells to CDDP by targeting CCND2." (PMID 34746018, 2021). "Furthermore, we examined the mechanisms underlying altered CCND2 AS1 expression and function by examining the methylation status of the CCND2 AS1 promoter in cervical cancer." (PMID 32607313, 2020). "However, further work will be required to verify these findings and to elucidate in more detail the molecular mechanisms by which CCND2 AS1 regulates the growth of cervical cancer." (PMID 32607313, 2020). "Thus, overexpression or knockdown of CCND2 AS1 caused a significant accumulation or reduction, respectively, of cervical cancer cells at the G1/S phase, indicating a block at the G1/S transition." (PMID 32607313, 2020). "Finally, we verified the in vivo relevance of the in vitro findings by confirming that the growth of cervical cancer tumors was significantly reduced by upregulation of CCND2 AS1." (PMID 32607313, 2020). "Expression of CCND2 AS1 was examined in cervical cancer and adjacent normal cervical tissues by quantitative real-time polymerase chain reaction (qRT-PCR) and by bioinformatic analysis of data from the Gene Expression Profiling Interactive Analysis (GEPIA) database." (PMID 32607313, 2020). "Collectively, our data suggest that CCND2 AS1 could be a novel diagnostic marker and/or a potential therapeutic target for cervical cancer." (PMID 32607313, 2020). "In the present study, we investigated CCND2 AS1 expression in fresh cervical tissues and in GEPIA datasets, and probed its function by overexpressing or silencing CCND2 AS1 in cervical cancer cell lines and analyzing the effects in vitro and in a mouse xenograft model." (PMID 32607313, 2020). "This is the first report that CCND2 AS1 acts as a tumor suppressor in cervical cancer." (PMID 32607313, 2020). "However, little is known about the expression and/or function of lncRNA CCND2 AS1 in cervical cancer." (PMID 32607313, 2020). "Thus, our findings reveal that OTUD6B-AS1, miR-206, and CCND2 may be useful therapeutic targets for overcoming CDDP resistance in patients with cervical cancer." (PMID 34746018, 2021). "However, whether OTUD6B-AS1 could regulate CDDP resistance in cervical cancer cells by upregulating CCND2 expression through protecting it from miR-206-mediated repression is unknown." (PMID 34746018, 2021).
cervical carcinoma (continued). "Our research showed that down-regulation of miR-206 led to the acquisition of CDDP resistance in cervical cancer cells, and the restoration of miR-206 attenuated CDDP resistance through targeting CCND2." (PMID 34746018, 2021). "The function of CCND2 AS1 was investigated by overexpressing or silencing CCND2 AS1 in HeLa and SiHa cervical cancer cells followed by in vitro and in vivo analyses." (PMID 32607313, 2020). "Overall, our findings shed new insights on the mechanisms of CDDP resistance and purport possible clinical application of targeting the OTUD6B-AS1/miR-206/CCND2 pathway as a promising way to reverse CDDP resistance and improve the prognosis of patients with cervical cancer." (PMID 34746018, 2021). "However, the relationship between CCND2 and miR-206 in cervical cancer has not been clarified." (PMID 34746018, 2021). "The lncRNA CCND2 AS1 has been shown to be involved in the growth of several tumors; however, its role in cervical cancer has not been elucidated." (PMID 32607313, 2020).
granulosa cell tumor (5 papers, 2004 to 2023). A slow-growing, malignant tumor, characterize by the presence of granulosa-like cells and Call-Exner bodies, that is almost always found in the ovary. "The expression of Myc, cyclin D2 and cyclinE2 was highly increased in BMPR1a and BMPR1b double knockout mice, which result in the promotion of granulosa cell tumor proliferation." (PMID 29409506, 2018). "Here, we show that TAF4B mRNA correlates with Cyclin D2 mRNA expression in human granulosa cell tumors." (PMID 24653979, 2014). "Synergistically with GATA-4 it activates the cyclin D2 (CCND2) promoter, a key factor for proliferation and survival in granulosa cell tumors." (PMID 36869369, 2023).
Insulin resistance (5 papers, 2019 to 2024). Increased resistance towards insulin, that is, diminished effectiveness of insulin in reducing blood glucose levels. "Cyclin D2 drives β cell compensation in response to insulin resistance, but islet cyclin D2 levels are reduced in Irs2–/– mice; rescue by Cdk4-R24C makes sense in this context." (PMID 37712417, 2023). "Cyclin D2, a driver of postnatal β cell expansion and β cell compensation for insulin resistance, binds to and activates cyclin-dependent kinase (CDK) family members CDK4 and 6 to hyperphosphorylate the retinoblastoma (Rb) protein and derepress E2F transcription factors." (PMID 37712417, 2023).
lymph node metastasis (5 papers, 2010 to 2023). "The levels of miR-206 and CCND2 were significantly correlated with TNM staging and lymph node metastasis." (PMID 36694220, 2023). "In contrast, patients without lymph node metastasis were found to have more frequent mutation in four genes including GATA3, FOXA1, ANKRD11, and RET (P<0.05) and more CN amplifications in two genes including PIK3C2G and CCND2 (P<0.05)." (PMID 33968723, 2021).
mantle cell lymphoma (5 papers, 2011 to 2025). Mantle cell lymphoma is a rare form of malignant non-Hodgkin lymphoma affecting B lymphocytes in the lymph nodes in a region called the ``mantle zone''. "Although the original diagnosis in this patient was CD5-positive DLBCL presumably transformed from the patient’s reported CLL/SLL, the presence of IGL::CCND2 raises the possibility of mantle cell lymphoma at initial diagnosis." (PMID 41374977, 2025). "This category would include CCND2, a protein closely related to proliferation, which has long been linked to outcome in DLBCL and mantle cell lymphomas." (PMID 21829609, 2011). "CCND2 and CCND3 rearrangements detected in most cyclin D1-negative mantle cell lymphoma represent a recurrent disease mechanism." (PMID 41374977, 2025).
nasopharyngeal carcinoma (5 papers, 2014 to 2024). A carcinoma arising from the nasopharyngeal epithelium. "For instance, FAM225B directly bound to miR-613, a miRNA targeting CCND2, resulting in CCND2 upregulation, facilitating nasopharyngeal carcinoma tumorigenesis and metastasis." (PMID 35037556, 2022). "In previous studies, miR-26a/b have been shown to block the G1/S transition of the cell cycle by targeting CCND2, CCNE1/2, CDK6, and EZH2 in HCC and nasopharyngeal carcinoma, and to restrain metastasis by suppressing the expression of IL6 in HCC." (PMID 24565101, 2014). "The upregulation of miR-124 has also been associated with reduced proliferation, migration, and invasion of nasopharyngeal carcinoma cells (C666-1 cells) via downregulation of STAT3, p-STAT3, G1/S-specific cyclin-D2 (CCND2) and Matrix Metalloproteinase-2 (MMP-2) expression in C666-1 cells." (PMID 36936170, 2023).
adenoma (4 papers, 2011 to 2024). A neoplasm arising from the epithelium. "For example, in a mouse model of adenoma formation, Apc dysfunction causes an increase in Cyclin D2 and CDK4 expression and a corresponding increase in hyperphosphorylated Rb35." (PMID 30655555, 2019). "USP8-mutated adenomas showed higher level of POMC, CDC25A, MAPK4 but lower level of CCND2, CDK6, CDKN1B than USP8-wild-type tumors." (PMID 38862897, 2024). "Recent work in our laboratory has shown that the cyclin D2-cyclin-dependent kinase 4/6 (CDK4/6) complex promotes hyperproliferation in Apc deficient intestinal tissue and ApcMin/+ adenomas." (PMID 21288356, 2011).
astrocytoma (4 papers, 2010 to 2025). "Except for CCND2, FLT1, FOXC2, KDR, KRT14, and TEK, the mRNA expression ratio of cancer pathway-associated genes in the astrocytoma grade III cell line (SW1088) was comparable to that of other tumour cell lines." (PMID 36142793, 2022). "We performed the same assays to evaluate Cyclin D2 promoter methylation in primary astrocytoma samples and found that the Cyclin D2 promoter was methylated/partially methylated in 14/44 (32%) of the tumors." (PMID 21059263, 2010). "Our observations on the expression of GLI1, Cyclin D2, and PTCH1 in astrocytoma cell lines as well as tumor samples revealed a significant proportion of samples showing low or null levels of Cyclin D2 and PTCH1, even in the presence of high GLI1 expression." (PMID 21059263, 2010). "On the contrary, we observed significant correlation of GLI1 expression with downstream target genes PTCH1 (p = 0.07), Cyclin D2 (p = 0.006), Plakoglobin (p = 0.02), PAX6 (p = 0.006) and NKX.2.2 (p = 0.0001) in astrocytoma cell lines." (PMID 21059263, 2010). "In non-TCGA IDH1/2-mutant astrocytomas, CCND2 alteration (HR: 3.05), EGFR amplification (HR: 2.43), CDKN2A/B loss (homozygous or heterozygous loss, HR: 2.28), 22q loss (HR: 1.97), and PDGFRA alteration (HR: 1.92) were negatively prognostic." (PMID 39164213, 2025). "However, treatment with these compounds resulted in the onset of Cyclin D2 expression, assessed by both RT-PCR and qRT-PCR in five astrocytoma cell lines that did not initially express Cyclin D2 (A172, SW1783, T98G, CCF-STTG-1 and GOS-3)." (PMID 21059263, 2010). "Six astrocytoma cell lines (U87MG, A172, LN405, SW1783, T98G and SW1783) expressed Cyclin D2 at very low levels, and two cell lines (CCF-STTG-1 and GOS-3) did not express Cyclin D2 compared to normal adult brain tissue (p = 0.006)." (PMID 21059263, 2010).
diabetic cardiomyopathy (4 papers, 2021 to 2024). Diabetic cardiomyopathy is a disorder of the heart muscle in people with diabetes. "It inhibited miR-150-5p expression and cyclin D2 (CCND2) production in diabetic cardiomyopathy, enhancing cardiomyocyte ferroptosis." (PMID 37731525, 2023). "Ni and team found that inhibiting the lncRNA ZFAS1 attenuates diabetic cardiomyopathy (DCM) progression via sponging of miR-150-5p to activate cyclin D2 (CCND2), which leads to reduced collagen deposition and inhibiting of cardiomyocyte apoptosis and ferroptosis." (PMID 38064139, 2024). "In diabetic cardiomyopathy, ZFAS1 induces ferroptosis by sponging miR-150-5p and activates CCND2 expression." (PMID 39296014, 2024).
diffuse large B-cell lymphoma (4 papers, 2010 to 2020). "In this study, cyclin D2 was found to be overexpressed in 98% of de novo CD5-positive diffuse large B-cell lymphomas (DLBCLs) (50/51) and in 28% of CD5-negative DLBCLs (14/51)." (PMID 23675804, 2013). "LMO2, MYBL1, BCL6, LRMP, and CCND2 in our 35 signature genes were also reported in Lossos's 36 genes, which predicted survival in diffuse large-B-cell lymphoma." (PMID 20856936, 2010). "In this study we investigated whether the expression of cyclin D2 (CCND2) mRNA in activated B-cell-like diffuse large B-cell lymphoma (ABC-DLBCL) was correlated with the efficacy of Rituximab combined with chemotherapy (R-CHOP) treatment and patient prognosis." (PMID 32850340, 2020).
lung adenocarcinoma (4 papers, 2017 to 2024). A carcinoma that arises from the lung and is characterized by the presence of malignant glandular epithelial cells. "The mechanism underlying the association of low CCND2 expression with lung adenocarcinoma and TNBC is interesting." (PMID 30308939, 2018). "Although organoid-derived subcutaneous tumors do not perfectly mimic the autochthonous BPN model, these data provide additional orthogonal evidence that Cyclin D2 plays a role in the response of NKX2-1-negative lung adenocarcinoma to MAPK inhibition." (PMID 33821796, 2021). "In this study, we identified a potential drug target, CCND2, for the treatment of TNBC and lung adenocarcinoma." (PMID 30308939, 2018). "Moreover, β-catenin, c-Myc, c-Jun, Cyclin D2 and PRC1 protein expression were examined by IHC in tissue sections of 25 lung adenocarcinoma." (PMID 28646916, 2017).
papillary thyroid carcinoma (4 papers, 2019 to 2023). "For instance, lncRNA GAS8‐AS1 suppresses papillary thyroid carcinoma growth through the miR‐135b/CCND2 axis." (PMID 33150698, 2021). "Additionally, in papillary thyroid cancer model, silencing of ETV5 causes a decrease in cell proliferation and this was associated with a diminished expression of CCND1 (cyclin D1) and CCND2 (cyclin D2)." (PMID 37876309, 2023). "The expression of miR-409-3p is reduced in papillary thyroid carcinoma and may negatively regulate cell proliferation and cell cycle progression through repression of its target gene, cyclin D2, in these tumors." (PMID 32391354, 2020).
prostate tumors (4 papers, 2012 to 2021). "There are few studies in literature on the hypermethylation of SCGB3A1 and CCND2 in prostate tumour tissue." (PMID 27576364, 2016). "The results showed that the mRNA levels of BAD, CCND2 and PDGF-D were differentially expressed in prostate tumor tissues and normal prostate gland." (PMID 28674394, 2017).
retinoblastoma (4 papers, 2018 to 2022). A malignant tumor that originates in the nuclear layer of the retina. "Seventh, miR-204 downregulation in retinoblastoma suggested that it may act as a tumor suppressor by targeting CCND2 and MMP9." (PMID 32070426, 2020). "High expression of cyclin-D2 and MMP-9 increases the cell division rate and progression of retinoblastoma." (PMID 34646884, 2021). "Cyclin-D2 and MMP-9 are two key genes that are regulated by miR-204 in retinoblastoma." (PMID 34646884, 2021).
sarcoma (4 papers, 2015 to 2022). A usually aggressive malignant neoplasm of the soft tissue or bone. "It has been reported that CCND2 was overexpressed due to either amplification of CCND2 genes or aberrant mitogenic signaling in several types of sarcoma." (PMID 26393798, 2015).
endometrial cancer (3 papers, 2000 to 2022). Primary or metastatic malignant neoplasm involving the endometrium (mucous membrane that lines the endometrial cavity). "Further investigations with different systems biology methods have prioritized ALDH1A1, ABL1 and CCND2 as potential genes involved in endometrial cancer metastasis owing to their high mutation load and expression status." (PMID 36704357, 2022). "In conclusion, this study identified key miRNAs (hsa-mir-200a, hsa-mir-429) and target genes ALDH1A1, ABL1 and CCND2 as potential biomarkers for metastatic endometrial cancers from large-scale gene expression data using systems biology approaches." (PMID 36704357, 2022). "We analysed p16 gene alteration and p16, cyclin-dependent kinase 4 (CDK4), CDK6, cyclin D1, cyclin D2, cyclin D3 and retinoblastoma protein (pRb) expression in ten normal endometriums (PE), 18 endometrial hyperplasias (EH) and 35 endometrial cancers (EC)." (PMID 10682682, 2000). "The upregulated hsa-mir-200a-b is associated with the decreased expression of the PTCH1, CCND2, PDGFRA, FOSB and ABL1 genes in endometrial cancer tissue while hsa-mir-429 is correlated with the decreased expression of the ALDH1A1 gene, besides some antibodies, PROTACs and inhibitory molecules." (PMID 36704357, 2022).
Ewing sarcoma (3 papers, 2015 to 2019). A small round cell tumor that lacks morphologic, immunohistochemical, and electron microscopic evidence of neuroectodermal differentiation. "Researchers have found that the introduction of miR-29b in Ewing's Sarcoma (ES) cells could inhibit the c-Myc-mediated up-regulation of CCND2, thus preventing the progression of the cell cycle." (PMID 29662889, 2018). "For example, researchers found that the introduction of miR-29b in Ewing's Sarcoma cells could inhibit the c-Myc-mediated upregulation of CCND2, which resulted in the prevention of cell cycle progression." (PMID 29662889, 2018). "In Ewing sarcoma, miR-124 expression is suppressed, and expression was found to reduce growth and metastasis via downregulation of mesenchymal genes such as SLUG and cyclin D2 (CCND2)." (PMID 31616462, 2019).
head and neck squamous cell carcinoma (3 papers, 2020 to 2025). A squamous cell carcinoma that arises from any of the following anatomic sites: lip and oral cavity, nasal cavity, paranasal sinuses, pharynx, larynx, and salivary glands. "The analysis revealed that high expression of CCND2 promotes proliferation and invasion in head and neck squamous cell carcinoma and clear cell renal cell carcinoma, establishing CCND2 as a risk factor for these malignancies." (PMID 40487928, 2025).
Hydrocephalus (3 papers, 2019 to 2024). Hydrocephalus is an active distension of the ventricular system of the brain resulting from inadequate passage of CSF from its point of production within the cerebral ventricles to its point of absorption into the systemic circulation. "Brain MRI abnormalities detected so far in individuals harboring CCND2 variants include hydrocephalus, ventriculomegaly, and PMG mainly in the perisylvian region." (PMID 31056854, 2019). "Megacephaly polymicrogyria, polydactyly, hydrocephalus (MPPH) is an extremely rare condition caused by a defect in the AKT3, CCND2, or PIKR2 genes." (PMID 34354878, 2021).
oral squamous cell carcinoma (3 papers, 2019 to 2025). "Likewise, in oral squamous cell carcinoma, BAP18 promotes cell cycle progression and proliferation by activating CCND1 and CCND2 transcription via MLL1 complex recruitment and H3K4me3 enrichment at their promoters." (PMID 40818609, 2025).
primary effusion lymphoma (3 papers, 2017 to 2025). A large B-cell lymphoma located in the body cavities, characterized by pleural, peritoneal, and pericardial fluid lymphomatous effusions and that is always associated with human herpes virus-8 (HHV-8). "Similarly, amino acid and DNA sequence analyses of KSHV, which has been strongly implicated as the etiologic factor in the development of Kaposi's sarcoma and primary effusion lymphomas (PEL), identified a “cyclin-box” showing similarity to human cyclin D2." (PMID 30510918, 2018). "Of note, p27KIP1 is also directed to proteasomal degradation in primary effusion lymphoma (PEL) by KSHV viral proteins, K-cyclin and V-cyclin, which are homologs of human cyclin D2 and form a complex with CDK4/6." (PMID 29160853, 2017).